CRP (C-reactive protein)
Diseases named in the same sentence as CRP in open-access papers (continued):
Sharing a sentence is not in itself a finding about the gene and the disease.
leukocytosis (continued). "Nine clinical and biological variables were extracted: shock index, peritonism, abnormal bowel sounds, fever (> 38 °C), intensity and duration of the pain, leukocytosis (white blood cell count >11G/L), relative lymphopenia (< 15% of total leukocytes), and C-reactive Protein (CRP)." (PMID 30658580, 2019). "Laboratory workup showed a leukocytosis 14 400 cells/μL with elevated CRP 109.6." (PMID 30186884, 2018). "Laboratory workup may show evidence of systemic inflammation with leukocytosis, and elevated CRP and ESR." (PMID 29397796, 2018). "Elevated leukocytosis and CRP values were observed at variable rates." (PMID 29643881, 2018). "Initial laboratory testing revealed marked leukocytosis (white blood cells, 24,730 cells/mm3), anemia (hemoglobin concentration of 6.9 g/dL), elevated C-reactive protein (CRP) 32.05 mg/dL (reference range, 0–0.5 mg/dL), hypoalbuminemia (albumin, 2.5 g/dL); and normal AST/ALT and BUN/creatinine." (PMID 30068330, 2018). "Furthermore, our study indicated that both leukocytosis and elevated CRP level played important roles in the motivation to prescribe antibiotics by their doctors." (PMID 30192893, 2018). "Acknowledging the small number of the patients in our study, it seems mandatory to design and implement future studies in which factors like leukocytosis, high CRP, high ESR, and hematuria as minor criteria are considered with an assessment of a greater number of IE cases." (PMID 28149706, 2017). "Leukocytosis, elevated C-reactive protein and AST level were noted in most of the patients." (PMID 28149700, 2017). "The blood examination revealed marked leukocytosis and elevated level of C reactive protein (CRP)." (PMID 28861738, 2017). "Most of the patients at that stage are febrile and present with a moderate leukocytosis and increased C-reactive protein concentrations, which was also true in our study group, suggesting that the inflammatory process in the periphery had not fully resolved yet." (PMID 28646884, 2017). "Routine hematological investigation revealed leukocytosis and high C-reactive protein (CRP)." (PMID 28533843, 2017). "Anemia, leukocytosis, higher CRP and sedimentation positivity were seen in colitis." (PMID 29232715, 2017). "Laboratory tests revealed leukocytosis and an increased serum CRP." (PMID 28421155, 2017). "Analysis of preoperative laboratory test results showed that high levels of C-reactive protein, leukocytosis, increased urine specific gravity, low hemoglobin, hyponatremia, hypokalemia, low serum protein, and low serum albumin were significant risk factors for postoperative delirium." (PMID 27015177, 2016). "While fever, leukocytosis and an elevated CRP are common in patients with TOA, about 40% of patients with TOA may have a normal temperature and leukocyte count, according to findings of the current study." (PMID 26894926, 2016). "The clinical disease course of the EBV infection was relatively unremarkable, but hepatosplenomegaly and inflammatory parameters (i.e. elevated ESR, CRP, leukocytosis, lymphocytosis, and hypergammaglobulinemia) were more pronounced compared to EBV infection in subjects with normal immune function." (PMID 26931784, 2016). "Comparing Gram-positive bacteria with Gram-negative bacteria, patients with Gram-positive-related infections demonstrated greater leukocytosis (12,631 versus 8,037, p=0.004) and tended to have higher CRP values (129.7 versus 84.9, p=0.098); however, the latter finding was not significant." (PMID 28076516, 2016). "In addition, leukocytosis with elevated erythrocyte sedimentation ratio and C-reactive protein declined to normal range at discharge." (PMID 26782665, 2016). "However, leukocytosis, thrombocytosis, high CRP and ESR, and fibrinogenemia can be found occasionally." (PMID 27965909, 2016). "All of the patients presented with leukocytosis and elevated C-reactive protein (CRP) levels." (PMID 27876028, 2016).
leukocytosis (continued). "In a multivariate analysis comparing between R018 and R017 infections, R018 infections caused a higher CRP level (1.04, 1.01–1.08, p = 0.021), less frequent hypoalbuminemia (0.41, 0.2–0.84, p = 0.014), but more frequent severe CDI assessed by leukocytosis and azotemia (1.88, 1.05–3.37, p = 0.034)." (PMID 28002482, 2016). "Routine laboratory examination including leukocytosis, C-reactive protein, and peripheral eosinophilia may be helpful but these are not specific to this disease." (PMID 27800471, 2016). "Leukocytosis and slightly high level of CRP (C-reactive protein) continued to be observed." (PMID 26428868, 2015). "The blood tests revealed leukocytosis [20,300 cells/μL (normal, 4,000–8,000 cells/μL) with 91.5% neutrophils, 0% eosinophils and 6.5% lymphocytes], elevated serum C-reactive protein levels [3.14 mg/dL (normal, <0.3 mg/dL)] and elevated serum LDH levels [341 U/l (normal, 106–220 U/l)]." (PMID 26090317, 2015). "This study main clinical findings (sudden behavioral changes in an old woman) and laboratorial tests (Leukocytosis with mild neutrophilia, high CRP, urine II with leukocyturia and erythrocyturia) lead the hypothesis of urinary infection." (PMID 26398362, 2015). "However, to the best of our knowledge, there is no study directly investigated the correlation of the levels of CRP, sedimentation and leukocytosis with the latency period." (PMID 28913037, 2015). "An elevated ESR >20 mm/h was observed in 40 patients (100%), an elevated CRP >0.8 mg/dL was observed in 40 patients (100%), leukocytosis ≥10,000/mm3 was observed in 26 patients (65%), and elevated ferritin levels ≥10,000 ng/mL were observed in 16 patients (40%)." (PMID 25929927, 2015). "After including laboratory results in the model, younger age, C-reactive protein, leukocytosis or leukopenia, low thrombocyte count, low sodium level, elevated urea and elevated arterial pH were added, while gastro-intestinal symptoms and hypotension were no longer significant." (PMID 26599636, 2015). "Laboratory data showed leukocytosis and elevation of C-reactive protein." (PMID 26366343, 2015). "Leukocytosis >13 000/mm3 and positive CRP were the most frequent laboratory findings, respectively." (PMID 26468481, 2015). "Blood tests revealed leukocytosis with elevated serum C-reactive protein levels." (PMID 26090317, 2015). "She returned to psychiatry and repeated the analyses that revealed leukocytosis 17,500x109/L with neutrophil (85.68%), CRP test 4.66mg/dL, urine II with leukocyturia (17cell/uL), erythrocyturia (37cell/uL) and negative nitrite test and normal thyroid functions." (PMID 26398362, 2015). "Other exclusion factors were haemoglobin <10 g/dL, CRP ≥10 mg/dL and reactive leukocytosis." (PMID 24642526, 2014). "Laboratory studies revealed leukocytosis (white blood cell count = 17,700/μL), elevated C-reactive protein (CRP; 12.20 mg/dL [reference range, 0.01–0.31 mg/dL]), serum aspartate aminotransferase (171 IU/L), and serum alanine aminotransferase levels (152 IU/L), and hyponatremia (sodium = 132 mEq/L)." (PMID 25349761, 2014). "Laboratory tests noticed leukocytosis (neutrophils 10.3 × 103/μL) and CRP was 1.4 mg/dL." (PMID 25431726, 2014). "Leukocytosis with neutrophilia, acidosis, altered coagulation profile, impaired renal function, raised creatine kinase levels, and raised inflammatory markers, such as C-reactive protein levels, are helpful if viewed within the whole of the clinical context." (PMID 24707295, 2014). "The complete blood count and laboratory examination will usually confirm leukocytosis and might reveal elevated C-reactive protein, erythrocyte sedimentation rate, or liver enzyme." (PMID 23365780, 2013). "Interestingly, DEP exposure induced a leukocytosis and a significant increase of CRP, indicating the occurrence of systemic inflammation." (PMID 23587270, 2013). "In addition, a substantial proportion of the patients had leukocytosis and elevated serum CRP>40 mg/L." (PMID 23300669, 2012).
leukocytosis (continued). "He had a tachycardia, pyrexia, leukocytosis and an elevated C-reactive protein (CRP)." (PMID 21251266, 2011). "Anemia, leukocytosis and high CRP were found, but bacterial blood culture was sterile." (PMID 21234200, 2010). "In addition, patients with MERS of unknown etiology, leukocytosis, and elevated serum CRP levels should be closely monitored because of the possibility of KD." (PMID 40881803, 2025). "Laboratory investigations demonstrated leukocytosis (20.3×109/L, 90% neutrophils), anemia (hemoglobin 9.5 g/dL), relative lymphopenia (1.5×109/L), hyponatremia (133 mmol/L), and elevated inflammatory markers (CRP (C-reactive protein) 23.9 mg/dL, procalcitonin 2.12 ng/mL)." (PMID 41141097, 2025). "Laboratory tests such as complete blood counts (CBC), complete metabolic panels (CMP), coagulation studies, creatinine kinase (CK) levels, and C-reactive protein (CRP) levels may be used to identify leukocytosis with neutrophilia, acidosis, altered renal function, and inflammatory markers." (PMID 41141183, 2025). "Initial laboratory investigations revealed leukocytosis of 20,050 cells/μL (reference: 3,600–10,500/μL) with 86% neutrophils, a normal blood glucose level of 91 mg/dL (reference: 70–110 mg/dL), and elevated C-reactive protein (CRP) at 2.4 mg/dL (reference: 0.0–2.0 mg/dL)." (PMID 40672814, 2025). "Initially, laboratory tests may be normal, or they may reveal a minimal inflammatory syndrome manifested by leukocytosis with or without neutrophilia and elevated C-reactive protein, secondary to caustic burns." (PMID 41375878, 2025). "When splenic torsion occurs, patients may have leukocytosis and elevated C-reactive protein." (PMID 40951031, 2025). "However, the patient developed a fever with a rising CRP, and leukocytosis." (PMID 39483118, 2024). "Notably, there was an inflammatory syndrome (C-reactive protein (CRP) at 122 mg/L; N < 5 mg/L) without associated leukocytosis, thrombocytopenia (52,000 platelets/mm3; N = 150-410/mm3), and hyperglycemia at 184 mg/dL (N = 70-110 mg/dL)." (PMID 39108773, 2024). "In the first cohort increased levels of C-reactive protein and/or erythrosedimentation rate was the most diffused laboratory findings at presentation (12 of 23 cases, 52%), followed by increased D-dimer (5/23, 22%), leukocytosis (4/23, 17%) and hypoalbuminemia (3/23, 13%)." (PMID 37500944, 2024). "In addition, these deaths were frequently (6/8 cases) associated with an elevation of C-reactive protein levels (2.63–36.0 mg/dL) without leukocytosis, including two patients with non-bacterial pneumonia." (PMID 36835957, 2023). "Laboratory tests showed leukocytosis (16.5 × 103/μL, 77% neutrophils), acute liver injury (bilirubin 2 mg/dL, aspartate aminotransferase 120 U/L, alanine transaminase 248 U/L), and elevated C-reactive protein (187 mg/L), ferritin (558 mcg/L), and D-dimer (2,698 ng/mL)." (PMID 35320702, 2022). "In contrast, other groups defined infection of the cerebrospinal fluid system by clinical symptoms and surrogate markers such as leukocytosis or elevated levels of the C-reactive protein, which are unspecific and may be pathological in other settings outside infection." (PMID 36009982, 2022). "For patients with infection of unknown origin, although specific pathogenic agents and infectious foci could not be identified, the etiology was considered to be infectious based on the presence of leukocytosis, leukopenia, and/or elevated C-reactive protein levels, among others." (PMID 35351159, 2022). "A nonspecific inflammatory syndrome can also be highlighted, characterized by a mild leukocytosis, increased erythrocyte sedimentation rate and increased C-reactive protein (CRP) value, but these are nonspecific and are associated with interstitial inflammation." (PMID 36553223, 2022). "However, in our study, after adjustment for potential confounders, neither leukocytosis nor the combination of leukocytosis and elevated CRP was independently associated with increased rate of sICH." (PMID 35622132, 2022).
leukocytosis (continued). "However, when high CRP levels and significant leukocytosis are observed in patients with acute enterocolitis, clinicians may prescribe antibiotics due to concerns about serious illness." (PMID 36670591, 2022). "Anemia (10.67 ± 1.87 in gm%) and leukocytosis (10182 ± 5842 cell/cumm) were present in 42.85% of patients, and inflammatory markers were significantly raised in most of the patients (high-sensitivity C-reactive protein (Hs-CRP) 84.5 ± 73.11 and erythrocyte sedimentation rate (ESR) 53.14 ± 14.67)." (PMID 34540476, 2021). "Anemia, leukocytosis, increased CRP and creatinine levels, low or high sodium and potassium levels as well as platelet count are associated with disturbed homeostasis and represent abnormalities that could be related to SARS-CoV-2 infection or concomitant diseases and their treatment." (PMID 34521357, 2021). "In addition to increased IL-1β release, the inflammatory episodes of MKD patients are characterized by an acute phase response, reflected by elevated erythrocyte sedimentation rates (ESR), leukocytosis and elevated serum levels of C-reactive protein (CRP) and serum amyloid A (SAA)." (PMID 34539662, 2021). "Laboratory tests may show leukocytosis and elevation of C-reactive protein." (PMID 33806811, 2021). "The leukocytosis level was significantly higher on day zero in the study group, but the value dropped markedly as early as on days two and three post-operatively; in turn, the CRP level was significantly lower in the group “methylprednisolone” as compared with the placebo group." (PMID 32940751, 2021). "Likewise, in line with the literature information, we identified a correlation between acute phase reactants and inflammatory biomarkers including leukocytosis, lymphopenia, CRP, cardiac troponin, D-dimer, fibrinogen, lactate dehydrogenase, ferritin, and serum albumin and mortality." (PMID 33315349, 2021). "First, although we had previously reported that a high DII diet before pregnancy is associated with leukocytosis in the first trimester, we did not measure plasma inflammatory markers, such as white blood cell, cytokines, such as CRP, IL-6, and TNFα, at the time of delivery in the present study." (PMID 33202775, 2020). "Also, 57 (78.1%) of the patients had positive CRP and 41 (50.6%) of the patients had leukocytosis." (PMID 32566310, 2020). "The symptoms of PES are typically followed by leucopenia, leukocytosis and/or elevation of C-reactive protein (CRP), which suggests that systemic manifestations of PES (fever, nausea, malaise) could be regarded as components of the systemic inflammatory response syndrome (SIRS)." (PMID 32878325, 2020). "Our study only partially confirms these results as it does effectively show an association between leukocytosis and the presence of abdominal pathology on CT, but it does not confirm the predictive role of CRP and patients with right iliac fossa pain were not included." (PMID 30658580, 2019). "Furthermore, the OPDA did not account for fistula risk score, patient age, leukocytosis, or c-reactive protein level despite these having been shown to be independent predictors of POPF development in other studies." (PMID 31827615, 2019). "Leukocytosis, CRP and ESR elevation, anemia, and growth in blood culture may be detected." (PMID 25685574, 2015). "Laboratory results showed leukocytosis (white blood cell (WBC) 17.2 × 109/L, neutrophils 14.6 × 109/L), hemoglobin 11.7 g/dL, and C-reactive protein (CRP) 37 mg/L; liver function and other tests were within normal limits." (PMID 41523228, 2026). "Laboratory tests revealed leukocytosis (WBC 15.2 × 109/L), elevated C-reactive protein (CRP 215 mg/L), metabolic acidosis (lactate 5.8 mmol/L), and impaired renal function consistent with his baseline ESRD." (PMID 41552799, 2026). "Laboratory tests revealed normocytic anemia (hemoglobin 10.2 g/dL), leukocytosis (WBC 13.6 × 109/L), elevated serum creatinine (130 μmol/L) and markedly increased C-reactive protein (CRP 220 mg/L)." (PMID 41446687, 2026).